ZNF33A (zinc finger protein 33A)
Description:
May be involved in transcriptional regulation.
Synonyms: ZZaPK; KIAA0065; KOX31; ZNF11; ZNF11A; ZNF33; KOX5; FLJ23404; KOX2; NF11A
Tractability: PROTAC: UniProt records ubiquitination sites on it; ubiquitination databases record sites on it.
Gene: Protein-coding gene on chromosome 10 (38,010,295 to 38,065,088, forward strand). Ensembl gene ENSG00000189180.
Subcellular location: Nucleus
Subcellular location (Human Protein Atlas): Endoplasmic reticulum; Nucleoli fibrillar center; Vesicles
Pathways (Reactome):
Gene expression (Transcription): Generic Transcription Pathway; Regulation of endogenous retroelements by KRAB-ZFP proteins
Gene Ontology:
Molecular function: DNA-binding transcription factor activity; transcription cis-regulatory region binding; double-stranded DNA binding; sequence-specific DNA binding
Biological process: negative regulation of transcription by RNA polymerase II; regulation of DNA-templated transcription
Cellular component: nucleus; nuclear lumen
Genetic constraint (gnomAD): Loss-of-function variants: 9 observed, 17.89 expected, observed/expected ratio (o/e) 0.5, 90% interval 0.3 to 0.88. The upper end of that interval is the gene's LOEUF score, 0.88, which puts it in group 3 of 6, group 1 being the genes least tolerant of losing a copy. Missense variants: 843 observed, 963.85 expected, observed/expected ratio (o/e) 0.87, 90% interval 0.83 to 0.93. Synonymous variants: 294 observed, 324.44 expected, observed/expected ratio (o/e) 0.91, 90% interval 0.82 to 1.
Homologues: Orthologues: chimpanzee ZNF33A (98% identical), macaque ZNF33A (89% identical). Paralogues in human: ZNF33B (89% identical), ZNF658 (38% identical), ZNF546 (37% identical), ZNF717 (36% identical), ZNF841 (36% identical), ZNF41 (36% identical), ZNF585B (36% identical), ZNF182 (35% identical), ZNF37A (35% identical), ZNF836 (35% identical), ZNF484 (34% identical), ZNF568 (34% identical), and 164 more.
Diseases named in the same sentence as ZNF33A in open-access papers:
ZNF33A is named in the same sentence as 1 disease in open-access papers, as found by Europe PMC text mining. Sharing a sentence is not in itself a finding about the gene and the disease.
ZNF33A shares sentences with these, for which no sentence is quoted: genetic diseases (1 paper).